ZIM2 (zinc finger imprinted 2)
Description:
May be involved in transcriptional regulation.
Synonyms: ZNF656
Tractability: No criterion of Open Targets' tractability assessment is met for any kind of drug.
Gene: Protein-coding gene on chromosome 19 (56,774,547 to 56,840,731, reverse strand). Ensembl gene ENSG00000269699.
Subcellular location: Nucleus
Subcellular location (Human Protein Atlas): Nuclear speckles; Cytosol
Pathways (Reactome):
Gene expression (Transcription): Generic Transcription Pathway
Gene Ontology:
Molecular function: protein binding; DNA-binding transcription factor activity; zinc ion binding
Biological process: regulation of DNA-templated transcription; regulation of transcription by RNA polymerase II
Cellular component: nucleus
Genetic constraint (gnomAD): Loss-of-function variants: 12 observed, 37.56 expected, observed/expected ratio (o/e) 0.32, 90% interval 0.2 to 0.52. The upper end of that interval is the gene's LOEUF score, 0.52, which puts it in group 2 of 6, group 1 being the genes least tolerant of losing a copy. Missense variants: 653 observed, 691.6 expected, observed/expected ratio (o/e) 0.94, 90% interval 0.88 to 1.01. Synonymous variants: 230 observed, 243.87 expected, observed/expected ratio (o/e) 0.94, 90% interval 0.85 to 1.05.
Homologues: Paralogues in human: ZNF546 (26% identical), ZNF30 (25% identical), ZNF461 (25% identical), ZNF267 (24% identical), ZNF571 (23% identical), ZFP14 (23% identical), ZNF606 (23% identical), ZFP28 (23% identical), ZNF33B (23% identical), ZNF540 (23% identical), ZNF565 (23% identical), ZFP82 (23% identical), and 164 more.
Diseases named in the same sentence as ZIM2 in open-access papers:
ZIM2 is named in the same sentence as 9 diseases in open-access papers, as found by Europe PMC text mining. Sharing a sentence is not in itself a finding about the gene and the disease. The quoted sentences say what the papers report.
pancreatic cancer (2 papers, 2022 to 2025). "Large-scale genomic analyses in pancreatic cancer have identified ZIM2 mutations, suggesting a potential role in tumorigenesis." (PMID 41009448, 2025).
esophageal cancer (1 paper, 2015). A primary or metastatic malignant neoplasm involving the esophagus. "These gene pairs were distinct across cancer types in general, but some simultaneously occurred in different cancers, e.g., NFATC4/FAT1 appeared in both endometrial and lung cancers and PEG3/ZIM2 appeared in skin and esophageal cancers." (PMID 26212640, 2015).
neuroblastoma (1 paper, 2025). Neuroblastoma (NB) is the most common solid, extracranial childhood tumor. "ZIM2 gene amplification was detected in 10 cases, 7 of which were neuroblastoma patients." (PMID 41009448, 2025).
ototoxicity (1 paper, 2025). damage to the ear, specifically the cochlea or auditory nerve as a result of some toxic stimulus, eg from a drug. "A significant correlation was found between ZIM2 gene amplification and the presence of ototoxicity (rho = 0.461, p = 0.003), especially in advanced-stage cancer patients with severe hearing loss (rho = 0.38, p = 0.017)." (PMID 41009448, 2025).
cancer (3 papers, 2015 to 2025). A tumor composed of atypical neoplastic, often pleomorphic cells that invade other tissues. "Our study identified the ZIM2 gene as a promising candidate biomarker that warrants further investigation for predicting susceptibility to cisplatin-induced ototoxicity in cancer treatment." (PMID 41009448, 2025). "In this study, we investigated the germline mutation alterations of ADAM6, SIX3, GNAS, NDUFV1, H19, DEFA4, and ZIM2 genes in 82 pediatric cancer patients treated with cisplatin." (PMID 41009448, 2025). "Although the role of ZIM2 in pediatric cancers remains largely unexplored, its imprinting and involvement in fundamental developmental pathways indicate that further investigation in pediatric contexts is warranted." (PMID 41009448, 2025). "This restricts our ability to determine whether ZIM2 amplification is a specific marker for ototoxicity or represents a broader genomic alteration among pediatric cancer patients." (PMID 41009448, 2025).
ZIM2 also shares sentences with these, for which no sentence is quoted: leukemia (1 paper); lung carcinoma (1); ovarian carcinoma (1); prostate carcinoma (1).